IGF1 (insulin like growth factor 1)
Diseases named in the same sentence as IGF1 in open-access papers (continued):
Sharing a sentence is not in itself a finding about the gene and the disease.
acromegaly (continued). "The correlations between structural and endocrine alterations to the thyroid and patient demographic characteristics, GH levels, and IGF-1 levels in acromegaly remain controversial." (PMID 29593792, 2018). "Determinants of mortality in acromegaly include a serum GH > 2.5 ng/mL and an elevated IGF-1 as well as hypertension, cardiovascular and cerebrovascular disease, and hypoadrenalism." (PMID 29563895, 2018). "We also examined various relationships between the IGFBP3 genotypes and glucose, lipid, phosphorus, kidney index, tumor volume, plasma GH level, and plasma IGF-1 before and after surgery in patients with acromegaly." (PMID 30619084, 2018). "A multiple logistic regression analysis demonstrated a significant correlation between the highest AASI value and serum IGF-1 (p = 0.034) across all acromegaly groups." (PMID 29643875, 2018). "In the guidelines, the upper limit of normal (ULN) was introduced as a surrogate for ‘safe’ IGF-1 levels which can be used to monitor the biochemical control of an individual acromegaly patient." (PMID 29605877, 2018). "Treatment of patients with acromegaly is aimed at normalizing GH and/or IGF1 levels to ameliorate signs and symptoms of the disease and reduce excess mortality." (PMID 30050156, 2018). "In patients with acromegaly and DI, the IGF-1 levels were significantly higher and the AHI was larger compared to patients without DI." (PMID 28620866, 2017). "Despite extensive clinical research, the question still arises as to which hormonal measurement, GH or IGF-1 (or both), is the best representation of the activity of acromegaly." (PMID 28733467, 2017). "Treatment of acromegaly is considered effective when patients achieve basal plasma GH levels below 1 ng/mL or glucose-suppressed GH levels below 0.4 ng/mL and normal IGF-1 levels 5-7." (PMID 28492721, 2017). "Elevated levels of growth hormone (GH) and insulin-like growth factor 1 (IGF-1) in patients with acromegaly lead to bone alterations and soft palate hypertrophy." (PMID 28620866, 2017). "The persistence of high levels of GH and IGF-1 in patients with acromegaly raises the mortality rate to 30%." (PMID 28490347, 2017). "The alteration of GH/IGF-1 signaling, caused by an excessive or a defective GH secretion, is associated with CV impairment both in GHD and in acromegaly." (PMID 29036907, 2017). "In principle, the fetal-placental collaboration between mother and child more-or-less takes over the control over GH and IGF-1, not only in normal physiology but also to a certain extend in acromegaly." (PMID 27568329, 2017). "The relation between GH/IGF1 excess and QoL is complex due limitations inherent to our current understanding of acromegaly." (PMID 28316591, 2017). "Only one of them had all pre-specified criteria for acromegaly diagnosis: IGF-1 persistently elevated, GH nadir >0.4 ng/mL and a pituitary microadenoma." (PMID 28898247, 2017). "The NDRG2 mRNA expression was significantly lower in the case of acromegaly (GH and IGF-1 hypersecretion) than in other diagnoses of PAs (p < 0.05)." (PMID 28390436, 2017). "Treatment of acromegaly/gigantism has advenced greatly in recent decades, and studies indicate that the strict control of GH/IGF-1 levels reduces morbidity and mortality 5,10,11." (PMID 28492721, 2017). "The persistence of plasma GH achieved in these studies is markedly different from the pathological states of elevated GH exposure, where Igf1 production shows major dysregulation in both GH resistance (IGF1 suppression) and acromegaly (IGF1 induction)." (PMID 28694329, 2017). "Up to 75% of patients with CNC exhibit asymptomatic elevation of GH, IGF-1, or prolactin, and 10% to 12% have acromegaly with detectable pituitary adenoma usually presenting at or after the third decade." (PMID 28973408, 2017).
acromegaly (continued). "Acromegaly is a rare condition characterized by growth hormone (GH) excess and elevated Insulin-like growth factor 1 (IGF-I) levels attributed in the vast majority of cases, to a pituitary adenoma." (PMID 27743174, 2017). "Treatment with CPAP is effective in controlling sleep disorders in patients with acromegaly, although the results for the normalization of GH/IGF-1 and the improvement of OSAS are controversial." (PMID 28490347, 2017). "Of note, one of the acromegaly cases, despite having a clearly elevated IGF-1 (2.8 x ULN), had GH suppression by glucose (nadir GH: 0.31 ng/mL)." (PMID 28898247, 2017). "Delays in diagnosis in patients that attend with multiple symptoms of acromegaly still occur as illustrated clearly by De and Foucault, leading to unnecessary exposure of excessive GH/IGF-1." (PMID 28733467, 2017). "It is known that different IGF-1 assays perform differently and that in a UK study, the diagnosis of acromegaly was inaccurately excluded in 30% of single samples assayed for IGF-1 in 23 different laboratories." (PMID 28898247, 2017). "Acromegaly is a disorder that is characterized by changes in growth hormone (GH), insulin-like growth factor-1 (IGF-1) and insulin concentrations and actions." (PMID 27568329, 2017). "In acromegaly patients, serum IGF-1 levels are high and they tend to have more multinodular diseases than other subjects." (PMID 29081797, 2017). "Serum insulin-like growth factor type 1 (IGF1) was measured in patients with ≥1 acral symptom to determine the prevalence of acromegaly." (PMID 28898247, 2017). "In principle, the placenta takes over the control over maternal GH and IGF-1 secretion, not only in normal physiology but also to a certain extend in acromegaly." (PMID 27568329, 2017). "If the 5 cases with persistently elevated IGF-1 in our study had been considered as having acromegaly, we would be facing a very high prevalence of the disease in this particular population." (PMID 28898247, 2017). "Acromegaly is an endocrine disorder characterized by increased circulating insulin-like growth factor-1 (IGF-1) levels usually due to a GH-secreting pituitary adenoma, leading to significant morbidity and excess mortality." (PMID 27966451, 2017). "IGF-1 levels (%ULN) were higher at diagnosis among younger acromegaly patients; this difference was significant for the study population overall and male patients but not females (P < 0.001)." (PMID 28733467, 2017). "In a case of suspected acromegaly, an elevated IGF-1 level and a failure to suppress GH below 1 ng/mL during an oral glucose tolerance test (OGTT) confirm the diagnosis." (PMID 27716353, 2016). "There are currently no prospective interventional studies demonstrating to what extent therapies that reduce GH and IGF-1 levels affect the incidence and prognosis of colon cancer in acromegaly." (PMID 28025627, 2016). "Surgery is considered first-line treatment and provides adequate control of cortisol levels in many patients with CD (65–90 %) and GH and IGF-1 levels in patients with acromegaly (microadenomas, >85 %; macroadenomas, 40–50 %)." (PMID 27405306, 2016). "The percentage of patients achieving the composite endpoint of both GH and IGF-1 control after 1 year of treatment in prospective studies of patients with previously untreated acromegaly was 17–27 % with octreotide LAR and 33–54 % with lanreotide Autogel." (PMID 26519143, 2016). "Based on their rarity, the knowledge of paraneoplastic syndromes occurring in patients with pulmonary NET such as acromegaly due to paraneoplastic GH- and IGF-1 secretion is mandatory to adequately diagnose and treat these patients." (PMID 27349224, 2016). "A recent consensus statement on the management of acromegaly advocates reducing GH and IGF-1 levels to as close to normal as possible (GH <1.0 μg/L [using an ultrasensitive assay] and IGF-1 within the normal range for age and sex)." (PMID 27039081, 2016).
acromegaly (continued). "For acromegaly at present only blood values of IGF-1 and GH are recommended to detect possible disease activity and to evaluate the results of therapy or possible complications in the follow-up period." (PMID 27932856, 2016). "Initial results of pegvisomant in patients with acromegaly (n = 160) showed that normal IGF-1 levels were achieved in 87 of the 90 (97 %) patients who received pegvisomant for at least 12 months." (PMID 27039081, 2016). "SSAs have been shown to improve acromegaly symptoms and limit GH/IGF-1 hypersecretion and tumor growth." (PMID 26603536, 2016). "In this Phase III study, biochemical control of acromegaly was defined according to targets recommended by clinical consensus guidelines at the time of study initiation (GH <2.5 μg/L and normal IGF-1)." (PMID 27039081, 2016). "The aims of treatment for acromegaly are to control/reduce tumour size, normalise GH and insulin-like growth factor 1 (IGF-1) levels and to improve comorbidities." (PMID 27458240, 2016). "Considering that IGF-1 is known to be responsible for most of the tissue trophic effects of GH, it is counterintuitive that patients with low IGF-1 can present with features of acromegaly." (PMID 26514337, 2015). "Evidence for increased bone formation rate and bone mass from exposure to IGF1 also comes from conditions such as acromegaly and rhGH treated children receiving long-term corticosteroid therapy." (PMID 25659076, 2015). "When SAs, possibly combined with cabergoline, fail to control acromegaly, pegvisomant, a GH-receptor antagonist, normalizes serum IGF1 levels in 70–97% of cases." (PMID 26429918, 2015). "The patient remains in fair clinical conditions, has a good control of acromegaly (January 2014: IGF-1 = 76 ng/ml) and his treatment still includes pegvisomant for acromegaly and tamoxifen for metastatic breast cancer." (PMID 25962899, 2015). "In keeping with this finding, normal IGF-1 levels have been reported in patients with poorly controlled diabetes who present with acromegaly, and it is recommended that IGF-1 be measured after hyperglycemia is controlled." (PMID 26514337, 2015). "The serum IGF-1 level is a good tool to use for assessment of integrated GH secretion and is recommended for diagnosis, monitoring, and screening of acromegaly." (PMID 26514337, 2015). "Based on the recently published Endocrine Society Clinical Practice Guideline on acromegaly, therapeutic goals include an age-normalized serum IGF-1 value and a random GH level <1 μg/L4." (PMID 26918140, 2015). "The acromegaly patients were also categorized according to their IGF-1 status (high or controlled) and analyses carried out for all measures in the study." (PMID 26078758, 2015). "Chronic excessive growth hormone and IGF-1 secretion in acromegaly cases affects cardiac morphology and performance, thereby inducing cardiomyopathy specific to this disease." (PMID 25250797, 2015). "A large, randomized, double-blind, Phase III core study demonstrated that pasireotide LAR was significantly superior to octreotide LAR at providing GH <2.5 μg/L and normalized IGF-1 after 12 months’ treatment in patients with acromegaly." (PMID 25103549, 2015). "The effect of pegvisomant on IGF1 levels in patients with acromegaly is well documented, but little is known of its long-term impact on comorbidity." (PMID 26429918, 2015). "The serum insulin-like growth factor-1 level provides an assessment of integrated growth hormone secretion and is recommended for diagnosis, monitoring, and screening of acromegaly." (PMID 26514337, 2015). "We report a case of a patient with acromegaly who presented with elevated GH, low IGF-1, and poorly controlled diabetes." (PMID 26514337, 2015). "Pegvisomant was associated with an increase in BMI, which had already started to increase after previous treatments for acromegaly; bodyweight changes thus seem to reflect the improvement in IGF1 levels." (PMID 26429918, 2015).
acromegaly (continued). "The nadir GH level was 21.4 ± 39.3 ng/mL (mean ± SD, range: 1.1–214.0 ng/mL), the fasting GH level was 27.4 ± 44.6 ng/mL (range: 2.7–276.0 ng/mL), and the IGF-1 level was 802.7 ± 337.5 ng/mL (range: 144.0–1591.0 ng/mL) in the acromegaly group." (PMID 26600803, 2015). "Unlike SAs, which inhibit not only GH but also insulin secretion, pegvisomant normalizes IGF1 levels in most patients with acromegaly and has beneficial effects on glucose metabolism because it does not modify insulin secretion." (PMID 26429918, 2015). "In selected patients with active acromegaly, long-term somatostatin analogue therapy has been demonstrated to effectively control GH and IGF-1 levels, induce tumor volume reduction and improve hypertension and cardiac performance." (PMID 25103549, 2015). "Acromegaly is a rare disease characterized with elevated levels of growth hormone (GH) and insulin like growth factor 1 (IGF1)." (PMID 25839036, 2015). "Estrogens, selective estrogen receptor modulators (SERMs), alone or in combination with SSA, have been observed to decrease IGF-1 in women and to improve symptoms of acromegaly." (PMID 26664461, 2015). "There were studies reporting a better acromegaly outcome in terms of better GH and/ or IGF1 control and tumor volume reduction in patients treated with SRA before surgery." (PMID 26664461, 2015). "We report a case of a patient with acromegaly secondary to a pituitary microadenoma who presented with low insulin-like growth factor-1." (PMID 26514337, 2015). "In conclusion, pasireotide LAR and octreotide LAR provide long-term inhibition of GH and IGF-1 in patients with acromegaly." (PMID 25103549, 2015). "We present a case of an elderly patient with acromegaly and poorly controlled diabetes with low IGF-1 at presentation." (PMID 26514337, 2015). "Arterial blood gas, effort oximetry and serum growth hormone (GH) and insulin-like growth factor I (IGF-1) were also assessed in the patients with acromegaly." (PMID 26648427, 2015). "Normalization of GH and IGF-1 after the first surgical treatment of acromegaly is obtained in 61.2% (range 37–88), based on 32 studies." (PMID 26137525, 2015). "Acromegaly is a rare condition characterized by growth hormone (GH) excess and elevated insulin growth factor 1 (IGF-1) levels attributed in the vast majority of cases to a pituitary adenoma." (PMID 26918140, 2015). "While studies of the effect of pegvisomant on surrogate outcomes such as the IGF1 level are numerous, the impact of this GH receptor antagonist on comorbidities of acromegaly is poorly documented, despite health authorities' growing demands for hard endpoints." (PMID 26429918, 2015). "Acromegaly is a chronic disease characterized by hypersecretion of growth hormone (GH) and insulin-like growth factor 1 (IGF-1)." (PMID 26082755, 2015). "Her serum insulin-like growth factor-1 level, measured after glycemic control was achieved with metformin and insulin, was elevated, which is characteristic of acromegaly." (PMID 26514337, 2015). "On the other hand, an increase in T-cell activity and a decrease in B-cell activity have been demonstrated in a very large cohort of patients with acromegaly, with high levels of serum GH and IGF-1." (PMID 24341939, 2014). "In acromegaly, higher serum GH and IGF-1 levels probably cooperate synergically with such a loop in promoting thyrocyte proliferation and transformation." (PMID 25019383, 2014). "The current consensus criteria for cure and remission of acromegaly are based on biochemical variables, i.e., normalization of elevated hormonal levels of the biomarkers growth hormone (GH) and/or insulin like growth factor-1 (IGF-1)." (PMID 25610427, 2014). "Patients with acromegaly having ECMDs or DM were older, moreobese and had longer disease duration and higher IGF1 levels(Z-score)." (PMID 24692509, 2014). "In contrast to total IGF1, IGF1 bioactivity was within the reference range in a considerable number of subjects with active acromegaly." (PMID 24692508, 2014).
acromegaly (continued). "On the other hand, the prevalence of adrenal lesions in sporadic cases of acromegaly is higher than in the general population, possibly due to the permissive role of growth hormone (GH) and insulin-like growth factor 1 (IGH1) on tumorigenesis." (PMID 25210615, 2014). "A cross-sectional study was carried out in 15 patients with active acromegaly based on clinical presentation, unsuppressed GH during an oral glucose tolerance test, and elevated total IGF1 levels (>+2 s.d.)." (PMID 24692508, 2014). "During a repeat GH suppression test, GH levels suppressed normally (nadir 0.07 ng/ml) with an IGF1 level in the reference range of 111 ng/ml, confirming successful treatment of the acromegaly." (PMID 24897038, 2014). "Our study suggests that measuring IGF1 bioactivity in subjects with active acromegaly provides information about the IGF1 system, which fundamentally differs from that obtained by common available IGF immunoassays." (PMID 24692508, 2014). "Many studies reported IGF-1 normalization or marked reduction in acromegaly patients treated with Pegvisomant (HQ)." (PMID 25245336, 2014). "Control of GH and IGF-1 is important in patients with acromegaly if mortality is to be reduced to expected levels." (PMID 23529827, 2014). "Acromegaly is a chronic disease resulting from excessive secretion of growth hormone (GH) and insulin-like growth factor-1 (IGF-1)." (PMID 25329702, 2014). "In conclusion, IGF1 bioactivity was within the reference range in a considerable number of patients with active acromegaly in contrast to total IGF1." (PMID 24692508, 2014). "The complex mechanism of the effect of GH and IGF-1 on bone metabolism is evidenced in various clinical conditions that determine osteoporosis such as glucocorticoid induced osteoporosis, acromegaly, GHD patients, and senile osteoporosis." (PMID 25147565, 2014). "Several analytical and physiological issues need to be taken into account when using GH and IGF-1 assays in the diagnosis and follow-up of patients with acromegaly." (PMID 24272033, 2014). "Two recent studies in patients with acromegaly demonstrated increased blood levels of klotho which returned to normal after normalization of GH and IGF-1 levels, suggesting that klotho expression or secretion is regulated by GH or IGF-I." (PMID 25198618, 2014). "The aim of the present study was to investigate the value of IGF1 bioactivity in the evaluation of active acromegaly and in the assessment of QoL in active acromegaly." (PMID 24692508, 2014). "To the best of our knowledge, we are the first to present data suggesting that increased S-Klotho levels are part of a physiological mechanism dampening IGF1 actions in active acromegaly patients." (PMID 24692508, 2014). "Biochemical documentation of acromegaly with varying combinations of basal and post-glucose GH as well as IGF-1 levels is provided in 10 of these 13 cases; PRL was measured in 7 and found to be elevated in three." (PMID 24119925, 2013). "The diagnosis of acromegaly was confirmed by an age adjusted IGF-1 level 4.8 times the upper limit of normal (ULN) and a basal and post glucose GH concentrations of 7.7 ng/mL and 2.5 ng/mL, respectively." (PMID 24119925, 2013). "Pegvisomant is generally well tolerated with a safety profile similar to that reported in clinical trials and can effectively reduce IGF1 in patients with acromegaly refractory to conventional therapy." (PMID 23469107, 2013). "By correcting the overproduction of GH and IGF-1, a recent meta-analysis suggests that the mortality for treated acromegaly patients was nearly equivalent to the mortality expected of the general population." (PMID 23054327, 2013). "The diagnosis of acromegaly was confirmed with elevated IGF-1 level (serum IGF-1: 550 ng/mL, normal ranges: 94–210) and failure to suppress GH levels with a 100 g oral glucose load." (PMID 23762662, 2013).